SLC6A8 (solute carrier family 6 member 8)
Diseases named in the same sentence as SLC6A8 in open-access papers (continued):
Sharing a sentence is not in itself a finding about the gene and the disease.
cancer (continued). "Herein, we found that SLC6A8 expression was negatively correlated with the stromal, immune, and estimate score in the majority of cancers." (PMID 36061183, 2022). "In order to assess the relationship between SLC6A8 expression and patients’ prognoses in 33 types of cancer, univariate cox regression analysis was performed based on data from TCGA." (PMID 36061183, 2022). "SLC6A8 expression was negatively correlated with stromal, immune, and estimate scores in the majority of cancers analyzed." (PMID 36061183, 2022). "The present study offers a novel insight into the roles of SLC6A8 in the oncogenesis and development of multiple common cancers." (PMID 36061183, 2022). "To investigate SLC6A8 expression pattern in various human cancers, we analyzed the transcriptome data acquired from TCGA database." (PMID 36061183, 2022). "Our next step is to confirm and elucidate the role of SLC6A8 across different cancers experimentally." (PMID 36061183, 2022). "ROC curve analysis results indicated that SLC6A8 expression was able to discriminate cancer patients with relatively good accuracy (AUC>0.5)." (PMID 36061183, 2022). "Specifically, the AUC value of three fourths of cancer exceeded 0.7, meaning that SLC6A8 was relatively accurate in identifying possible cancer patients." (PMID 36061183, 2022). "In this work, we sought to thoroughly investigate the function of SLC6A8 in various cancers by integrating complementary bioinformatics methods and public databases." (PMID 36061183, 2022). "The results of gene expression analysis showed that SLC6A8 was upregulated in most types of the cancers while downregulated in a few types of cancers as compared to their corresponding normal counterparts." (PMID 36061183, 2022). "According to the results of the survival analysis, SLC6A8 expression predicted poor overall survival and disease-free survival of cancer patients." (PMID 36061183, 2022). "To summarize, our study uncovered the expression profile and clinical significance of SLC6A8 in pan-cancer through bioinformatics analysis for the first time." (PMID 36061183, 2022). "Considering the involvement of SLC6A8 in multiple physical and pathological processes, we sought to comprehensively explore the roles this gene plays in cancers through bioinformatics analysis." (PMID 36061183, 2022). "The expression of SLC6A8 exhibited the strongest positive correlation with that of ADM, GPI, NDRG1, PGK1, and PNCK, and their correlation with SLC6A8 expression in distinct cancer types were illustrated by the heatmap, respectively." (PMID 36061183, 2022). "Recently, SLC6A8 was reported to be involved in the malignant progression of several cancers, including NSCLC, CRC, and HCC via regulation of key signaling pathways." (PMID 36061183, 2022). "The receiver operating characteristic curves showed that SLC6A8 was relatively accurate in identifying possible cancer patients." (PMID 36061183, 2022). "There is mounting evidence on the implication of SLC6A8 in the initiation and progression of human cancers." (PMID 36061183, 2022). "As illustrated by the heatmap, SLC6A8 expression had significantly positive correlation with these MMR genes in 8 types of cancer, including BRCA, HNSC, LIHC, LUSC, OV, PRAD, STAD, and UCEC." (PMID 36061183, 2022). "The results revealed that SLC6A8 was differentially expressed in various cancers, with SLC6A8 expression significantly higher in LUAD and LUSC than in normal tissues (P-value<0.05)." (PMID 35251966, 2022). "This PCr was then imported into the cancer cells via SLC6A8 and generated ATP, thus enabling metastatic cancer cells to sustain their energetic requirements despite the physiologically hypoxic O2 levels in the normal liver." (PMID 34572020, 2021). "Next, creatine phosphate is taken up by cancer cells through SLC6A8 and is used to generate ATP and support survival of metastatic cells." (PMID 26191006, 2015).
cancer (continued). "At this moment, finding potent inhibitors of SLC6A6 and SLC6A8, which may be tested in cancer cell lines, seems to be a challenge for scientists." (PMID 36835201, 2023). "Besides, ROC curve was used to evaluate the clinical prediction accuracy of SLC6A8 in 27 cancer types." (PMID 36061183, 2022). "In general, SLC6A8 is significantly upregulated across multiple cancers." (PMID 36061183, 2022). "Nevertheless, analysis of the role of SLC6A8 in pan-cancer remains unexplored." (PMID 36061183, 2022). "Taken together, SLC6A8 was aberrantly expressed in diverse cancers." (PMID 36061183, 2022). "Next, creatine phosphate is taken up by a cancer cell via SLC6A8." (PMID 26191006, 2015). "However, a comprehensive understanding of the role of SLC6A8 in pan-cancer remains elusive yet." (PMID 36061183, 2022). "Taken together, SLC6A8 might be a potential prognostic and predictive factor in various cancers." (PMID 36061183, 2022). "Finally, the immunological roles of SLC6A8 in various cancers were evaluated." (PMID 36061183, 2022). "Mechanistically, VTN upregulates SLC6A8 expression in CRC cells and macrophages by enhancing FAK phosphorylation, which increases creatine and ATP uptake, promoting cancer progression and macrophage polarization." (PMID 40538300, 2025). "After creatine is transported into the cell through SLC6A8 or directly synthesized through GATM/GAMT, it can react with intracellular signals and promote cancer growth." (PMID 39769038, 2024). "However, the oncogenic roles of SLC6A8 across different cancers remain unknown." (PMID 36061183, 2022). "Thus, SLC6A8 represents an essential part of a unique mechanism where creatine phosphate, a compound containing a high energy phosphate bond (∼P), is directly delivered into cancer cell, providing a substrate for transfer of its phosphoryl group to ADP and the generation ATP." (PMID 26191006, 2015). "The aberrant expression of SLC6A8 predicts poor survival and distinguishes cancer patients from those without cancer in numerous cancers." (PMID 36061183, 2022). "Remarkably, SLC6A8 was showed to be able to discriminate cancer patients from those without cancer in 26 of 27 types of cancer (AUC >0.5)." (PMID 36061183, 2022). "A panel of six genes (CCNE2, DKFZp762E1312, EMP2, MAL2, PPIC and SLC6A8) were over-expressed in cancer cell lines and were absent in healthy women." (PMID 29132396, 2017). "Here, cancer cells may upregulate and release creatine kinase‐B (CKB) into the extracellular space where it generates the high‐energy metabolite phosphocreatine that is transported into the cell by the SLC6A8 transporter protein." (PMID 40903981, 2025).
metabolic disorders (4 papers, 2022 to 2024). "Hence, loss of SLC6A8 expression could induce metabolic disorders and can usually be found in IBD patients." (PMID 35893911, 2022). "Three had potentially treatable metabolic disorders (SLC2A1, COQ4 and SLC6A8)." (PMID 35979408, 2022).
genetic diseases (2 papers, 2021 to 2026). "Our results document robust network disruption in CTD and demonstrate that CTD pathology can be partially alleviated by perinatal genetic expression of SLC6A8, providing a foundation for the future development of experimental therapies for this genetic disorder." (PMID 40729420, 2026).
mental dysfunction (2 papers, 2019 to 2025). "Individuals with genetic Cr disorders characterized by mental dysfunction, including arginine–glycine amidinotransferase (AGAT), guanidinoacetate methyltransferase (GAMT), or solute carrier family 6 member 8 (SLC6A8) deficiencies, have also been shown to benefit from early Cr supplementation." (PMID 39816485, 2025).
infection (1 paper, 2020). The state of being infected such as from the introduction of a foreign agent such as serum, vaccine, antigenic substance or organism. "With regard to creatine metabolism, expression of creatine synthesis enzyme genes GATM and GAMT decreased as a result of Mtb infection, while the creatine transporter SLC6A8 and creatine kinase (brain-type, CKB) were increased, most notably in our M2 infection model." (PMID 32341411, 2020).
SLC6A8 also shares sentences with these, for which no sentence is quoted: Rett syndrome (3 papers); X-linked adrenoleukodystrophy (3); Angelman syndrome (2); colitis (2); Dystonia (2); glioblastoma (2); heart failure (2); lung squamous cell carcinoma (2); neurodevelopmental disorder (2); sarcopenia (2); 22q11.2 deletion syndrome (1); Arrhythmia (1); autism spectrum disorder (1); bladder cancer (1); brain disorder (1); Cachexia (1); cardiomyopathy (1); Cerebral atrophy (1); cerebral hypomyelination (1); Cerebral ischemia (1); cervical squamous cell carcinoma (1); cholangiocarcinoma (1); chronic renal failure (1); clear cell renal cell carcinoma (1); colorectal tumors (1); depression (1); developmental delay (1); diffuse large B-cell lymphoma (1); EARS disease (1); endocervical adenocarcinoma (1).
A further 46 diseases each share a sentence with SLC6A8 in 1 paper.